ENSG00000301067 (novel transcript)
Gene: Long non-coding RNA gene on chromosome 19 (1,021,516 to 1,021,883, forward strand). Ensembl gene ENSG00000301067.
Gene Ontology:
Molecular function: U4 snRNA binding
Biological process: formation of quadruple SL/U4/U5/U6 snRNP; spliceosomal tri-snRNP complex assembly
Cellular component: U4/U6 x U5 tri-snRNP complex; U6 snRNP